TNS1 (tensin 1)
Diseases named in the same sentence as TNS1 in open-access papers (continued):
Sharing a sentence is not in itself a finding about the gene and the disease.
gastric cancer (4 papers, 2022 to 2025). A primary or metastatic malignant neoplasm involving the stomach. "TNS1 demonstrates validated prognostic utility in bladder, colorectal, and gastric cancers, where its incorporation into multi-gene signatures predicts survival outcomes." (PMID 40906372, 2025). "To discover the function of COL14A1 and TNS1 in gastric cancer cells directly, we performed siRNA knockdown in human AGS cell line with two different siRNA sequences." (PMID 35515139, 2022). "Analysis of TNS1–3 expression in 90 gastric cancer patients revealed that the TNS3 protein was more frequent in moderately differentiated tumors compared to poorly/non-differentiated types, suggesting a potential role in promoting tumorigenesis rather than metastasis." (PMID 40906372, 2025). "In gastric cancer, TNS1 promotes proliferation and metastasis by enhancing cell contraction." (PMID 40858565, 2025). "Similarly, in gastric cancer (GC), TNS1 expression was elevated in peritoneal metastases compared to primary tumors, and its knockdown significantly reduced cell proliferation." (PMID 40906372, 2025).
acute myeloid leukemia (3 papers, 2021 to 2023). Acute myeloid leukemia (AML) is a group of neoplasms arising from precursor cells committed to the myeloid cell-line differentiation. "Down-regulated TNS1 suppresses the proliferation of acute myeloid leukemia cells and increases the apoptosis." (PMID 33269380, 2021). "The upregulation of TNS1 expression reverses the effects of prazosin in acute myeloid leukemia." (PMID 36358270, 2022). "TNS1, TNS3 and TNS4 knockdown reduces the proliferation of several cancer cell lines, such as colon cancer and acute myeloid leukemia cell lines." (PMID 37510408, 2023).
chronic obstructive pulmonary disease (3 papers, 2019 to 2023). A chronic and progressive lung disorder characterized by the loss of elasticity of the bronchial tree and the air sacs, destruction of the air sacs wall, thickening of the bronchial wall, and mucous accumulation in the bronchial tree. "For example, variants in TNS1 were related to chronic obstructive pulmonary disease." (PMID 33269380, 2021). "These patients may also be associated with abnormal mitral valves and wound-healing processes as observed in Tns1-KO mice, as well as chronic obstructive pulmonary disease, which TNS1 has been identified as a high-risk gene for through genome-wide association studies." (PMID 37374025, 2023).
colon cancer (3 papers, 2015 to 2025). "Like CRIPTO, TNS-1 and GAS-7, the other two genes in the associated regions present in the network, are both involved in breast and colon cancer." (PMID 25629528, 2015).
cystic kidney disease (3 papers, 2019 to 2023). A congenital or acquired kidney disorder characterized by the presence of renal cysts. "It is highly possible that a subgroup of human patients with cystic kidney diseases is associated with TNS1 aberrant expressions and/or mutations." (PMID 37374025, 2023). "TNS1 was implicated in cystic kidney diseases by TNS1 knockout mouse models that developed small, but significant, cortical and medullary cysts, ultimately leading to death from renal failure." (PMID 32513820, 2020). "Do aberrant TNS1 expression/mutations lead to cystic kidney diseases in humans?" (PMID 37374025, 2023). "The renal phenotype observed in Tns1-KO mice has been suggested as one of the animal models of cystic kidney disease showing genetic recessive inheritance and renal defect onset at adulthood." (PMID 37374025, 2023). "With the obtained findings, we further investigated the potential therapeutic strategy for cystic kidney diseases using TNS1-KO mice." (PMID 31740667, 2019). "Therefore, analyses of mutant mice with cystic kidneys, such as Tns1-KO mice, contributes to a deeper understanding of and better treatments for a variety of cystic kidney diseases." (PMID 37374025, 2023). "Interestingly, TNS1 has previously been shown to interact with NPHP1, a causal gene underlying a second cystic renal disease, nephronophthisis." (PMID 32513820, 2020).
mitral valve prolapse (3 papers, 2019 to 2025). A fairly common and often benign valvular heart disorder characterized by redundancy or hooding of mitral valve leaflets so that they prolapse into the left atrium, often causing mitral regurgitation. "Alterations in TNS1 lead to cardiac valve defects causing mitral valve prolapse, as is also observed in MFS patients." (PMID 34895303, 2021).
breast tumor (2 papers, 2020 to 2022). "In addition, Kaplan–Meier survival analysis showed an increased expression level of TNS1 in breast tumors, further suggesting an active role of TNS1 in MaTAR25-mediated breast tumor progression." (PMID 36358270, 2022).
cystic kidney (2 papers, 2019 to 2023). "Deficiencies in TNS1 or TNS2 result in CKD displaying cystic kidneys or NS, respectively." (PMID 37374025, 2023). "Despite all these findings, the molecular mechanism leading to the formation of cystic kidneys and eventual renal failure caused by TNS1 deficiency remains unclear." (PMID 31740667, 2019). "Nonetheless, because TNS1-KO mice develop cystic phenotypes progressively, are fertile, and live almost half of the normal mouse lifespan, it is very likely that a group of human cystic kidney patients display similar symptoms caused by mutations or aberrant expression of TNS1." (PMID 31740667, 2019). "In this report, we have established a 3D MDCK TNS1-KO cell system, which develops into cysts with multiple lumens that mimic cystic kidney defects observed in TNS1 knockout mice." (PMID 31740667, 2019). "TNS1 (tensin-1) knockout mice develop cystic kidneys and die from renal failure." (PMID 31740667, 2019). "Although no human cystic kidney patient associated with TNS1 mutations has been reported so far, the likelihood is very high based on the finding that Tns1-KO mice are able to produce offspring, develop renal defects progressively, and have half the normal life expectancy." (PMID 37374025, 2023). "Currently, there is no known human cystic kidney patient that is caused by TNS1 mutation." (PMID 31740667, 2019).
leiomyosarcoma (2 papers, 2022 to 2025). An uncommon, aggressive malignant smooth muscle neoplasm, usually occurring in post-menopausal women. "An emerging fusion partner of ALK, TNS1, was recently described in uterine leiomyosarcomas; we observed this fusion in 16 cases (12 cases in uterine and non-uterine LMS) in the current cohort." (PMID 35705558, 2022). "We also reported TNS1-ALK fusions in two uterine sarcomas, and a case report described a patient with leiomyosarcoma benefiting from matched therapy with the ALK inhibitor brigatinib after failing multiple lines of chemotherapy." (PMID 40711866, 2025).
liver cancer (2 papers, 2015 to 2025). An epithelial or non-epithelial malignant neoplasm that arises from the liver. "Subsequently, in the MHCC-97H liver cancer cell line with endogenous VEZF1 knockout, silencing TNS1 gene inhibited the promoting effect of VEZF1WT on HCC progression." (PMID 40858565, 2025).
lung adenocarcinoma (2 papers, 2020 to 2023). A carcinoma that arises from the lung and is characterized by the presence of malignant glandular epithelial cells. "Phospho-TNS1 was highly elevated in EMT cells after TGFβ treatment and was specifically observed in tissue samples of patients with poor-prognosis lung adenocarcinoma." (PMID 32315285, 2020).
lymph node metastasis (2 papers, 2020 to 2023). "In the present study, we demonstrate that low expression of TNS1 is associated with advanced T stages and lymph node metastasis." (PMID 33231563, 2020). "Based on the chi-square test, we found low expression of TNS1 correlated with lymph node metastasis in BCa patients." (PMID 33231563, 2020).
melanoma (2 papers, 2015 to 2019). A malignant, usually aggressive tumor composed of atypical, neoplastic melanocytes. "Overexpression of the IGFBP5 mediator of insulin-like growth factor receptor (IGF1R) signalling inhibits the transformation of human melanoma cells in culture whilst TNS1 expression is down-regulated in multiple cancers including melanoma." (PMID 31881017, 2019).
metastatic tumors (2 papers, 2021 to 2022). "TNS1 was also more often observed in metastatic tumors compared to those without distant metastases (p = 0.001)." (PMID 33926026, 2021). "TNS1 expression was more frequently observed in metastatic tumors (21.43% of patients) compared to cancers without distant metastases (1.61% of patients) (p = 0.001)." (PMID 33926026, 2021).
non-small cell lung carcinoma (2 papers, 2021 to 2025). A group of at least three distinct histological types of lung cancer, including non-small cell squamous cell carcinoma, adenocarcinoma, and large cell carcinoma. "Furthermore, TNS1 drives the growth and metastasis of non-small-cell lung cancer (NSCLC) cells via the Akt/mTOR/RhoA pathway." (PMID 40906372, 2025).
polycystic kidney (2 papers, 2019 to 2020). "Deletion of the focal adhesion molecule Tns1 in mice caused polycystic kidney disease and glomerulosclerosis (Lo, Yu, Degenstein, Chen, & Fuchs, 1997), suggesting a critical role for Tns1 in maintaining intact cell‐matrix junctions in tubular epithelial cells and podocytes." (PMID 32400101, 2020). "Altogether, our data suggest that TNS1-KO 3D culture mimics the polycystic kidney phenotype observed in TNS1-KO mice." (PMID 31740667, 2019).
biliary tract cancer (1 paper, 2025). "Oncogenic fusions involving tensins include TNS1::BRAF in BRAF-negative papillary thyroid carcinomas (identified in a cohort of 62 cases) and FGFR2::TNS1 detected in circulating tumor DNA from biliary tract cancer patients (102 cases)." (PMID 40906372, 2025).
brain cancer (1 paper, 2014). A primary or metastatic malignant neoplasm affecting the brain. "In a recent study, TBIs have been associated with an increased risk for brain cancer, suggesting that this TNS1 activity may increase morbidity risks following TBI." (PMID 25346719, 2014).
cyst (1 paper, 2019). A sac-like closed membranous structure that may be empty or contain fluid or amorphous material. "In this study, we have generated an in vitro TNS1-KO MDCK cell system to determine the molecular mechanism leading to cyst formation and validated the in vitro results in KO mice." (PMID 31740667, 2019). "Here, we have established TNS1-knockout MDCK cells and applied 3D culture system to investigate the mechanism leading to cyst formation." (PMID 31740667, 2019).
endometriosis (1 paper, 2025). The growth of functional endometrial tissue in anatomic sites outside the uterine body. "They acknowledged the need for future research to investigate TNS1 expression across different endometriosis phenotypes and to further elucidate its role in disease progression." (PMID 40072086, 2025). "The relevance of TNS1 in endometriosis was further addressed in a commentary by Barra and Ferrero, who highlighted the importance of understanding the molecular mechanisms underlying TNS1’s role in ectopic endometrial cell adhesion and migration." (PMID 40072086, 2025). "The evidence presented in the available studies highlights the critical role of TNS1 in cell adhesion and migration, processes that are central to the development and progression of endometriosis." (PMID 40072086, 2025). "However, further research is needed to characterize TNS1’s role in other subtypes of endometriosis and to clarify its mechanistic contributions to disease pathophysiology." (PMID 40072086, 2025).
gastric tumors (1 paper, 2021). "TNS1 expression was over three times more frequent in non-differentiated gastric tumors than in the poorly differentiated type, whereas no TNS1 was detected in moderately differentiated tumors." (PMID 33926026, 2021).
gastrointestinal stromal tumor (1 paper, 2025). "Clinically, tensin dysregulation correlates with metastasis and poor prognosis: TNS2 serves as a diagnostic biomarker for gastrointestinal stromal tumors, aberrant TNS1/TNS3 expression predicts metastasis risk, and TNS4 is recurrently embedded in multi-gene prognostic signatures." (PMID 40906372, 2025).
glomerular disease (1 paper, 2024). "Even if the role of GJA5, TNS1, and CCND1 in glomerular disease requires further investigation (beyond the scope of this work), they might represent a biomarker signature of progressive glomerular damage, independent of the etiology." (PMID 38516889, 2024).
Hypertension (1 paper, 2021). The presence of chronic increased pressure in the systemic arterial system. "We also identified 21 DEGs (e.g., Fn1, Cd34, Plpp3, Tns1, Nox4, and Npnt) that may be involved in the development of hypertension." (PMID 34862465, 2021).
keloid (1 paper, 2021). An irregularly shaped, elevated mark on the skin caused by deposits of excessive amounts of collagen during wound healing. "Of note, TNS1 was identified as one of the ten most significantly regulated genes in keloids, which are benign fibroproliferative tumors in abnormal wound healing." (PMID 33923324, 2021).
Kidney Cyst (1 paper, 2020). Abnormal fluid filled sac within the kidney, either acquired or congenital. "We explored alterations in tensin-1 protein abundance in human kidney cysts from ADPKD patients and found an almost complete depletion of the tensin-1 protein in the cystic tissue as compared to levels in normal human kidney tissue (n=4 control samples and n=5 ADPKD cysts)." (PMID 32513820, 2020).
kidney degeneration (1 paper, 2021). "TNS1 is known to be essential for the formation of fibrils in extracellular vesicles and myofibroblast differentiation during embryogenesis, while the absence of TNS1 leads, inter alia, to kidney degeneration." (PMID 33926026, 2021).
kidney tumors (1 paper, 2022). "In addition, TNS1 expression is downregulated in human kidney tumors, and further studies have suggested that the upregulation of TNS1 expression may serve as an anti-cancer metastasis therapeutic strategy." (PMID 36358270, 2022).
leukemia (1 paper, 2025). A malignant (clonal) hematologic disorder, involving hematopoietic stem cells and characterized by the presence of primitive or atypical myeloid or lymphoid cells in the bone marrow and the blood. "Conversely, TNS1 exerts oncogenic effects in colorectal, gastric, liver cancers, and leukemia." (PMID 40906372, 2025). "Beside solid tumors, TNS1 also promotes growth of leukemia cells." (PMID 40906372, 2025).
lung fibrosis (1 paper, 2021). "TNS1 has been associated with increased ECM production in kidney disease and myofibroblast differentiation in lung fibrosis, where TNS1 is up-regulated by TGF-β." (PMID 33923324, 2021).
medulloblastoma (1 paper, 2021). A malignant, invasive embryonal neoplasm arising from the cerebellum. "Incidentally, CAG repeats were recently associated with three genes potentially involved in medulloblastoma: RAI1, BCL6B, and TNS1." (PMID 33765058, 2021).
metastasis (1 paper, 2025). The spread or migration of cancer cells from one part of the body (where they first appeared) to another. "Using LASSO Logistics analysis, they identified four genes (COL14A1, TNS1, NUSAP1, YWHAE) linked to peritoneal metastasis (PM) occurrence, where high COL14A1/TNS1 expression increased PM risk." (PMID 40906372, 2025).
osteosarcoma (1 paper, 2013). A usually aggressive malignant bone-forming mesenchymal neoplasm, predominantly affecting adolescents and young adults. "PR domain-containing 16 gene (PRDM16) is a known oncogene implicated in acute myeloid leukaemia (AML) and osteosarcoma Tensin 1 gene (TNS1) is the only gene present in the relevant FMCR, and TNS1 overexpression in vitro was previously shown to significantly promote cell migration in fibroblasts." (PMID 24367615, 2013).
pancreatic cancer (1 paper, 2026). "TNS1 expression occurred more frequently among patients with tumor diameter ≥ 2 cm, which may suggest an association with the development of pancreatic cancer." (PMID 41923376, 2026).
tear (1 paper, 2022). "TNS1 expression is decreased in ruptured ACL in patients with a meniscal tear compared to patients without meniscal injury." (PMID 36531249, 2022).
Tetralogy of Fallot (1 paper, 2025). A congenital cardiac malformation comprising pulmonary stenosis, overriding aorta, ventricular septum defect, and right ventricular hypertrophy. "Five of the probands with RGs in TNS1 had valve abnormalities affecting the mitral, pulmonary, or aortic valve as part of their CHD, including three with tetralogy of Fallot." (PMID 40030011, 2025).
triple-negative breast carcinoma (1 paper, 2016). An invasive breast carcinoma which is negative for expression of estrogen receptor (ER), progesterone receptor (PR), and human epidermal growth factor receptor 2 (HER2). "Expression of TNS1 decreased the migration and invasion of triple-negative breast cancer cells." (PMID 27626693, 2016).
viral infection (1 paper, 2022). "Interestingly, not only is the full-length NS1 protein expressed in influenza A virus-infected cells, N-terminus-truncated NS1 (tNS1) proteins can also be produced during viral infection." (PMID 35889979, 2022).